RASA4B (RAS p21 protein activator 4B)
Description:
Ca(2+)-dependent Ras GTPase-activating protein, that may play a role in the Ras-MAPK pathway.
Tractability: Antibody: UniProt places it where antibodies can reach, with medium confidence; its Gene Ontology location is reachable by antibodies, with medium confidence. PROTAC: ubiquitination databases record sites on it.
Gene: Protein-coding gene on chromosome 7 (102,479,976 to 102,517,800, reverse strand). Ensembl gene ENSG00000170667.
Subcellular location: Cytoplasm, cytosol; Cell membrane
Subcellular location (Human Protein Atlas): Vesicles; Cell Junctions
Gene Ontology:
Molecular function: GTPase activator activity; phospholipid binding
Biological process: regulation of intracellular signal transduction; cellular response to calcium ion; intracellular signal transduction; negative regulation of Ras protein signal transduction
Cellular component: plasma membrane; cytosol
Genetic constraint (gnomAD): Loss-of-function variants: 1 observed, 2.37 expected, observed/expected ratio (o/e) 0.42, 90% interval 0.14 to 1.65. That is too few expected variants to judge how well the gene tolerates losing a copy. Missense variants: 4 observed, 21.12 expected, observed/expected ratio (o/e) 0.19, 90% interval 0.092 to 0.43. Synonymous variants: 2 observed, 7.94 expected, observed/expected ratio (o/e) 0.25, 90% interval 0.1 to 0.79.
Homologues: Orthologues: macaque RASA4B (96% identical), guinea pig Rasa4b (88% identical), rat Rasa4 (87% identical), dog RASA4B (87% identical), mouse Rasa4 (86% identical), tropical clawed frog rasa4 (68% identical), zebrafish rasa4 (62% identical), Drosophila melanogaster raskol (28% identical), Drosophila melanogaster RasGAP1 (27% identical), Caenorhabditis elegans gap-2 (17% identical), Caenorhabditis elegans gap-1 (17% identical). Paralogues in human: RASA4 (99% identical), RASAL1 (49% identical), RASA3 (31% identical), RASA2 (30% identical), NF1 (27% identical), RASAL2 (23% identical), DAB2IP (22% identical), RASA1 (19% identical), RASAL3 (17% identical).
Diseases named in the same sentence as RASA4B in open-access papers:
RASA4B is named in the same sentence as 1 disease in open-access papers, as found by Europe PMC text mining. Sharing a sentence is not in itself a finding about the gene and the disease. The quoted sentences say what the papers report.
breast carcinoma (1 paper, 2015). "We selected 11 regions from genes ASMTL and RASA4B for Sanger validation in the breast cancer cohort (Supplementary Text Section 5)." (PMID 25820428, 2015).